PES1 (pescadillo ribosomal biogenesis factor 1)
Diseases named in the same sentence as PES1 in open-access papers (continued):
Sharing a sentence is not in itself a finding about the gene and the disease.
pancreatic cancer (4 papers, 2019 to 2023). "c-Myc is regulated transcriptionally by PES1 in pancreatic cancer cells, but the underlying mechanism remains unclear." (PMID 31718704, 2019). "Firstly, we suppressed the expression levels of PES1 in pancreatic cancer cells using specific short hairpin RNA (shRNA)." (PMID 31718704, 2019). "We found that Roscovitine, Dinaciclib, and JQ1 repressed the protein level of PES1 in pancreatic cancer cells." (PMID 31718704, 2019). "We established that the expression of PES1 was abnormally increased in pancreatic cancer tissues and led to poor prognosis of pancreatic cancer patients." (PMID 31718704, 2019). "In this study, we demonstrated that PES1 inhibition increases the sensitivity of pancreatic cancer cells to BET inhibitors (JQ1)." (PMID 31718704, 2019). "Owing to PES1’s role in cancer cell resistance to JQ1 in pancreatic cancer and Dinaciclib’s ability to destabilize PES1, we next explored the synergistic effect of JQ1 and Dinaciclib in pancreatic cancer cells." (PMID 31718704, 2019). "We observed that the mRNA and protein levels of c-Myc decreased after the knockdown of PES1 in pancreatic cancer cells." (PMID 31718704, 2019). "MTS, CCK8, BrdU cell proliferation assay, and colony formation assay were used to determine cell growth ability after knocking down PES1 in pancreatic cancer cells." (PMID 31718704, 2019). "We observed that the knockdown of PES1 by shRNA profoundly blocked pancreatic cancer cell growth and decreased Ki-67 positive cells in the tumor." (PMID 31718704, 2019). "Given that PES1 plays a significant role in pancreatic cancer cell proliferation in vivo and in vitro, a specific cell signaling pathway targeting molecules assay was employed to investigate the regulatory mechanism of PES1 in pancreatic cancer cells." (PMID 31718704, 2019). "Here, we examine the expression level of PES1 in pancreatic cancer patient specimens to determine its clinical significance and explore its biological role in pancreatic cancer cells." (PMID 31718704, 2019). "We revealed that PES1 expression in pancreatic cancer cells was higher than that in healthy pancreatic ductal epithelial cells (HDPE6-C7)." (PMID 31718704, 2019). "Collectively, our results indicate that c-Myc is regulated by PES1 and acts as a significant mediator of PES1-induced cell proliferation in pancreatic cancer cells." (PMID 31718704, 2019). "To verify PES1’s role in the sensitivity of pancreatic cancer cells to BET inhibitors, we established stable PES1 knockdown pancreatic cancer cells using mixed shPES1 (shPES1m)." (PMID 31718704, 2019). "Our data demonstrate that the inhibition of PES1 markedly slowed down pancreatic cancer proliferation in vitro." (PMID 31718704, 2019). "Our data, therefore, indicate that PES1 silencing mediated the sensitivity of PANC-1 cells to BET inhibitors in pancreatic cancer." (PMID 31718704, 2019). "The expression level of PES1 in pancreatic cancer cell lines and pancreatic cancer patient samples was determined using Western Blotting analysis, RT-qPCR analysis, immunohistochemical (IHC) analysis of tissue microarray, and the GEPIA web tool." (PMID 31718704, 2019). "We also found that high expression levels of PES1 resulted in shorter survival times in pancreatic cancer patient specimens." (PMID 31718704, 2019). "Therefore, our data suggest that PES1 acted as a growth-promoting protein for pancreatic cancer cells in vivo and in vitro." (PMID 31718704, 2019). "Similarly to results obtained with the GEPIA web tools, PES1 was up-regulated significantly in pancreatic cancer tissues." (PMID 31718704, 2019). "Given PES1’s clinical importance to pancreatic cancer patients, we considered whether PES1 had any effect on the biological behavior of pancreatic cancer cells." (PMID 31718704, 2019). "We have shown that PES1 could be one of the promoting factors of tumor growth and a prognosis-related protein of pancreatic cancer." (PMID 31718704, 2019).
pancreatic cancer (continued). "Our research has demonstrated that overexpressed PES1 could be considered a prognostic biomarker for pancreatic cancer patients; PES1 promoted pancreatic cancer growth in vivo and in vitro." (PMID 31718704, 2019). "However, the biological role and clinical significance of PES1 in pancreatic cancer are still unexplored." (PMID 31718704, 2019). "We next investigated the relationship between PES1 and c-Myc in pancreatic cancer patient specimens via tissue microarray and found that PES1 protein expression levels correlated positively with c-Myc expression levels (Spearman correlation coefficient r = 0.3345, P = 0.0495)." (PMID 31718704, 2019). "Targeting PES1 with CDK5 inhibitors might help overcome cancer cell resistance to BET inhibitors in pancreatic cancer cells." (PMID 31718704, 2019). "These assessments suggest that PES1 is aberrantly expressed in pancreatic cancer." (PMID 31718704, 2019). "PES1 mRNA expression levels also correlated positively with Myc in pancreatic cancer patients." (PMID 31718704, 2019). "In conclusion, we not only showed that PES1 had a tumor growth-promoting effect in pancreatic cancer but also demonstrated that combining Dinaciclib with JQ1 could inhibit tumor growth in mouse xenograft models." (PMID 31718704, 2019). "PES1 also contributes to cancer cell resistance to BET inhibitors in pancreatic cancer." (PMID 31718704, 2019). "Additionally, we found that PES1 transcriptionally increased the expression of c-Myc in pancreatic cancer cells through interaction with BRD4, and PES1 might function as an activator to enhance BRD4 activity in pancreatic cancer cells." (PMID 31718704, 2019). "Moreover, we found that BET inhibitors (JQ1) impeded the interaction between PES1 and BRD4 or the bromodomain of BRD4 (BD1 and BD2) in pancreatic cancer cells, which suggested that PES1 might bind to the bromodomain of BRD4." (PMID 31718704, 2019). "Thus, our data indicate that overexpressed PES1 might be a prognostic biomarker for pancreatic cancer." (PMID 31718704, 2019). "As a consequence, we pondered whether PES1 was overexpressed in pancreatic cancer." (PMID 31718704, 2019). "However, the role of PES1 in pancreatic cancer is poorly understood." (PMID 31718704, 2019). "Pescadillo ribosomal biogenesis factor 1 (PES1), which has been reported as an independent poor prognostic factor in pancreatic cancer patients, is essential for 60S ribosomal subunit maturation and pre-rRNA processing." (PMID 33134380, 2020). "Collectively, our data suggest that PES1 interacted with BRD4 and initiated the transcription of Myc in pancreatic cancer cells." (PMID 31718704, 2019). "Thus, we examined whether CDK5 regulates PES1 in pancreatic cancer." (PMID 31718704, 2019). "Given the connections between c-Myc, PES1, and BET inhibitors, we explored the possibility of an interaction between PES1 and BRD4 in pancreatic cancer cells." (PMID 31718704, 2019). "We also found that PES1 was responsible for promoting cell growth and contributed to bromodomain and cancer cell resistance to extra-terminal (BET) inhibitors in pancreatic cancer." (PMID 31718704, 2019). "After PES1 knockdown, the results of MTS, CCK8, BrdU cell proliferation and colony formation assays showed that the proliferation ability of pancreatic cancer cells decreased, while in mice, the Ki-67 protein level and the proliferative ability of pancreatic cancer cells were reduced." (PMID 34976188, 2022). "Our findings revealed that the co-knockdown of c-Myc and PES1 did not inhibit cell growth further, compared to the knockdown of c-Myc alone in pancreatic cancer cells." (PMID 31718704, 2019). "Then, the knockdown of CDK5 decreased the protein expression levels of PES1 but not mRNA levels in pancreatic cancer cells, consistent with the results obtained after Dinaciclib treatment." (PMID 31718704, 2019). "The specific role of PES1 in pancreatic cancer is, however, still not clear." (PMID 31718704, 2019).
pancreatic cancer (continued). "Moreover, Western Blotting analysis of 11 pairs of pancreatic cancer patients with adjacent non-tumor pancreatic tissues revealed that PES1 was highly present in pancreatic cancer tissues." (PMID 31718704, 2019). "Also, the tissue microarray of pancreatic cancer, containing 21 cases of non-tumor pancreatic tissue samples and 35 cases of pancreatic cancer tissue specimens, was subjected to immunohistochemical (IHC) analysis to evaluate the expression of PES1." (PMID 31718704, 2019). "Moreover, knocking down PES1 increased the sensitivity of pancreatic cancer cells to BET inhibitors, AKT inhibitors and mTOR pathway inhibitors, and decreased the mRNA and protein levels of c-Myc, which is related to the sensitivity of pancreatic cancer cells to BET inhibitors." (PMID 34976188, 2022).
prostate carcinoma (4 papers, 2019 to 2023). A carcinoma that arises from epithelial cells of the prostate gland. "As indicated by microarray-based analysis, PES1 was screened as a DEG associated with the progression of prostate cancer and was a downstream mRNA of miR-1271." (PMID 32448371, 2020). "Through the analysis of microarray data in an online database, PES1 was identified as a differentially expressed gene which was upregulated in prostate cancer." (PMID 34976188, 2022). "PES1-silenced prostate cancer cells showed reduced EdU incorporation rates, increased apoptosis rates and reduced cell migration and invasion capabilities (all p <0.05)." (PMID 34976188, 2022). "The tumor-promoting effect of PES1 in prostate cancer can be inhibited by miR-1271, because miR-1271 targeted PES1 and downregulated its expression." (PMID 34976188, 2022). "PES1 was identified as a prostate cancer-related DEG and found to be upregulated in prostate cancer." (PMID 32448371, 2020). "miR-1271, which was poorly expressed in both cells and tissues of prostate cancer, can specifically bind to PES1." (PMID 32448371, 2020). "Based on the bioinformatic prediction and dual-luciferase reporter gene assay in the current study, PES1 is a potent target gene of miR-1271 in prostate cancer." (PMID 32448371, 2020). "Given the correlation of PES1 expression to the development of prostate cancer by microarray-based analysis, we aimed to explore the specific effects of PES1 on the development of prostate cancer." (PMID 32448371, 2020). "Taken together, overexpression of miR-1271 downregulates PES1 to activate the ERβ signaling pathway, leading to the delayed prostate cancer development." (PMID 32448371, 2020). "Our microarray-based analysis revealed that pescadillo homolog 1 (PES1) gene was differentially expressed in prostate cancer and was involved in the prostate cancer development." (PMID 32448371, 2020). "PES1 gene is upregulated in the microvesicles of prostate cancer cells and involved in the pathogenesis of prostate cancer." (PMID 32448371, 2020). "More importantly, overexpression of miR-1271 or silencing of PES1 suppressed prostate cancer cell proliferation, migration, and invasion as well as tumor growth, but promoted cell apoptosis." (PMID 32448371, 2020). "Our findings provide evidence that miR-1271 downregulated PES1 to activate the ERβ signaling pathway, which further inhibited the biological processes of prostate cancer." (PMID 32448371, 2020). "Overexpression of miR-1271 or depletion of PES1 inhibited prostate cancer cell proliferation, migration and invasion, promoted apoptosis in vitro and suppressed tumor growth in vivo." (PMID 32448371, 2020). "Initially, we found that PES1 was highly expressed while miR-1271 was marginally expressed in prostate cancer." (PMID 32448371, 2020). "We then examined the role of PES1 in prostate cancer progression via the ERβ signaling pathway." (PMID 32448371, 2020). "Taken together, these results indicated that miR-1271 could downregulate PES1 to inhibit prostate cancer cell proliferation, migration, and invasion along with tumor growth and simultaneously, potentiate cell apoptosis." (PMID 32448371, 2020). "Further analysis of the prostate cancer datasets in The Cancer Genome Atlas (TCGA) indicated that PES1 gene expression was greatly upregulated in prostate cancer samples, which was in consistent with the gene expression in the prostate cancer-related expression datasets." (PMID 32448371, 2020). "Taken together, our results demonstrated that overexpression of miR-1271 could potentially repress the progression of prostate cancer via activation of the ERβ signaling pathway by downregulating PES1." (PMID 32448371, 2020). "We then further elucidated whether miR-1271 participates in prostate cancer progression by regulating PES1." (PMID 32448371, 2020).
prostate carcinoma (continued). "Based on these findings and analyses, we hypothesized that the interaction among miR-1271, PES1 and ERβ may participate in the progression of prostate cancer." (PMID 32448371, 2020). "However, more efforts are necessary to elucidate the clinical effects of miR-1271 and PES1 in prostate cancer and relevant diseases in the future studies." (PMID 32448371, 2020). "Also, cells transfected with sh-NC or sh-PES1 plasmids were injected into the nude mice to investigate the role of PES1 in prostate cancer in vivo." (PMID 32448371, 2020). "Collectively, PES1 might play an important role in the development of prostate cancer." (PMID 32448371, 2020).
esophageal squamous cell carcinoma (3 papers, 2023 to 2025). Esophageal squamous cell carcinoma (ESCC) is a type of esophageal carcinoma (EC) that can affect any part of the esophagus, but is usually located in the upper or middle third. "PES1 prevents IL-15 expression in esophageal squamous cell carcinoma (ESCC) by interfering with the relationship between ILF3 and IL-15 mRNA, which in turn promotes the breakdown of mRNA." (PMID 40097979, 2025). "Additionally, PES1 knockdown increased T-cell infiltration into subcutaneous tumors of Esophageal Squamous Cell Carcinoma (ESCC), promoting ESCC progression." (PMID 40787468, 2025).
head and neck squamous cell carcinoma (3 papers, 2012 to 2023). A squamous cell carcinoma that arises from any of the following anatomic sites: lip and oral cavity, nasal cavity, paranasal sinuses, pharynx, larynx, and salivary glands. "Protein microarray analysis revealed overexpression of PES1 in head and neck squamous cell carcinomas (HNSCCs), which was validated by Western blot and tissue microarrays containing 98 HNSCC specimens." (PMID 22860098, 2012). "However, in head and neck squamous cell carcinoma (HNSCC), the role of PES1 on the prognosis and immune infiltration remains unknown." (PMID 37076985, 2023).
hepatocellular carcinoma (3 papers, 2021 to 2023). A malignant tumor that arises from hepatocytes. "Previous studies have reported that PES1 plays a critical role in the progression of various cancers, including gastric, breast, pancreatic, colorectal and hepatocellular carcinoma." (PMID 36217758, 2023). "PES1 is upregulated and improves hepatocellular carcinoma cells proliferation." (PMID 34650978, 2021).
chronic myeloid leukemia (2 papers, 2023 to 2024).
schizophrenia (2 papers, 2021 to 2025). A major psychotic disorder characterized by abnormalities in the perception or expression of reality. "We identified two new schizophrenia risk loci, including associations in SHISA9 (rs7192086, P = 4.92 × 10-08) and PES1 (rs57016637, P = 2.33 × 10−11) in Han Chinese population." (PMID 34380480, 2021).
type 2 diabetic (2 papers, 2022 to 2023). "In summary, our current findings demonstrate that KD may ameliorate lipid deposition in type 2 diabetic mice by downregulating PES1 modulated acetylation of SREBP1c and inflammation pathways." (PMID 34979900, 2022).
anorexia nervosa (1 paper, 2025). A disorder most often seen in adolescent females characterized by a refusal to maintain a minimally normal body weight, an intense fear of gaining weight, a disturbance in body image, and, in postmenarcheal females, the development of amenorrhea. "For the anorexia nervosa and depression pair, despite the limited number of significant genes in both disorders, MAAT identified two genes, ARHGAP1 and PES1, that exert a significant impact on these two diseases." (PMID 39905509, 2025).
astrocytoma (1 paper, 2021). "The expression of WDR12 and Pes1 were both significantly upregulated in astrocytoma, oligodendroglioma, and GBMs compared to that in normal brains." (PMID 34868955, 2021).
brain tumors (1 paper, 2016). "PES1 is mainly expressed in developing tissues, but aberrant expression of PES1 has been found in human brain tumors." (PMID 27409667, 2016).
Candida infection (1 paper, 2018). "Pes1 regulates lateral yeast cell production but not hyphal morphology or biofilm architecture and has been shown to be essential for sustained candidiasis." (PMID 30131358, 2018).
coloboma (1 paper, 2022). An abnormality in which a part of a structure in one or both eyes is missing. "Ribosomal proteins other than Rpl5 also affect proper eye as well as brain development as Pescadillo homologue 1 (Pes1) and Peter Pan (Ppan) lead to malformed eyes, including coloboma, as well as microcephaly in developing Xenopus laevis." (PMID 35281111, 2022).
diabetes (1 paper, 2023). "The KD suppressed the diabetes‐induced increase in PES1, which may result in vascular hyperpermeability through ubiquitination of VE‐cadherin in type 2 diabetic mice." (PMID 37060584, 2023).
ear infection (1 paper, 2024). A viral or bacterial infection that affects the external, middle, or inner ear. "This low level of PES1 expression is not unique to the ear infection site and we have found similarly low levels of PES1 expression in both infected kidney and tongue 24 h post-infection." (PMID 38501830, 2024).
glioma (1 paper, 2021). A benign or malignant brain and spinal cord tumor that arises from glial cells (astrocytes, oligodendrocytes, ependymal cells). "However, the levels of WDR12, but not of Pes1, were higher in high-grade gliomas than that in low-grade gliomas." (PMID 34868955, 2021).
leukemia (1 paper, 2025). A malignant (clonal) hematologic disorder, involving hematopoietic stem cells and characterized by the presence of primitive or atypical myeloid or lymphoid cells in the bone marrow and the blood. "For instance, genes like ANGPT1, PES1, and ZNF222 demonstrated promoter active demethylation by both compounds and are known for promoting cell survival and proliferation of different types of leukemia." (PMID 41516186, 2025).
oral squamous cell carcinoma (1 paper, 2023). "In this study, we found that PES1 was negatively correlated with immune cells such as CD8+ T cells, macrophages, B cells, Treg cells, and neutrophils, and may be one of the relevant genes affecting the tumor microenvironment of oral squamous cell carcinoma." (PMID 37076985, 2023).
Sepsis (1 paper, 2024). Sepsis is defined as life-threatening organ dysfunction caused by a dysregulated host response to infection. "Thus, it can be currently considered that EBNA1BP2 and PES1 may be involved in the pathological process of sepsis and SIM by regulating the number and function of B lymphocytes." (PMID 39438952, 2024).
skin cancer (1 paper, 2023). "We also found genes that, to our knowledge, have no previously reported driver NCVs with TFA-BT NCVs in at least 5% of tumors within certain cancer types, such as RPL13A (bladder and skin cancer), TEDC2 (skin cancer), and PES1 (skin cancer)." (PMID 36808133, 2023).